TET2 (tet methylcytosine dioxygenase 2)
Diseases named in the same sentence as TET2 in open-access papers (continued):
Sharing a sentence is not in itself a finding about the gene and the disease.
neurodevelopmental disorder (1 paper, 2020). A behavioral and cognitive disorder with onset during the developmental period that involves impaired or aberrant development of intellectual, motor, or social functions. "The DNA demethylase TET2 is dysregulated in first-generation DNE rodents, and TET2 dysfunction is broadly linked to myriad epigenetic and phenotypic alterations which mirror those observed in neurodevelopmental disorders as well as first- and second-generation DNE offspring." (PMID 32138755, 2020).
psychiatric disorder (1 paper, 2023). A disorder characterized by behavioral and/or psychological abnormalities, often accompanied by physical symptoms. "Our findings, therefore, provide novel mechanistic insights into the role of epigenetic modification induced by Tet2 in chronic stress, suggesting the pathological importance of cytoplasmic Tet2 and RNA 5hmC modification in psychiatric disorders." (PMID 37091805, 2023).
TET2 also shares sentences with these, for which no sentence is quoted: leukocytosis (5 papers); Lymphadenopathy (4); acute myocardial infarction (3); breast (3); breast tumors (3); oral cancer (3); pancreatic cancer (3); autism (2); enteropathy-associated T-cell lymphoma (2); fibrosis (2); hyperlipidemia (2); kidney cancer (2); laryngeal carcinoma (2); multiple myeloma (2); myeloid sarcoma (2); Myocardial fibrosis (2); oropharyngeal cancer (2); overlap syndromes (2); pulmonary fibrosis (2); pulmonary hypertension (2); small intestinal neuroendocrine tumors (2); T-cell leukemia (2); acute monocytic leukemia (1); acute promyelocytic leukemia (1); alcohol (1); amyotrophic lateral sclerosis (1); Arthritis (1); ataxia telangiectasia (1); Atopic Dermatitis (1); bladder cancer (1).
A further 95 diseases each share a sentence with TET2 in 1 paper.